IL21 (interleukin 21)
Diseases named in the same sentence as IL21 in open-access papers (continued):
Sharing a sentence is not in itself a finding about the gene and the disease.
tumor (continued). "In this study, we have assessed whether IL-21 is able to influence Treg induction in the setting of tumour-derived immunosuppressive factors." (PMID 28239749, 2017). "However, tumour growth was comparable between WT and Il21−/− mice demonstrating that the effect seen in the Grail−/−Il21−/− and Grail−/− mice was due to the enhanced IL-21R signalling in the absence of Grail." (PMID 28798332, 2017). "However, the combination of IL-21 and IL-2 supports expansion while also increasing the ability of Vγ2Vδ2 T cells to kill tumor cells and produce inflammatory cytokines." (PMID 28239463, 2017). "Thus, in addition to its documented ability to prevent de novo Treg generation, IL-21 is able to maintain this effect in the context of tumour-derived milieus that actively promote FOXP3 expression." (PMID 28239749, 2017). "When given in vivo in mice, IL-21 boosts anti-tumor immunity." (PMID 28239463, 2017). "In vivo adoptive immunotherapy (AIT) experiments demonstrated anti-tumor efficacy was equally effective using IL-2, IL-21, IL-2/21, IL-7/15 and IL-7/15/21-cultured lymphocytes vs. control or cyclophosphamide alone, even at lower doses or with greater initial size of tumor prior to treatment." (PMID 28146052, 2017). "Collectively, our results suggest that IL-21 could restore the function of exhausted Tim-3+PD-1+ NK cells and effectively inhibit tumour progression." (PMID 28585539, 2017). "Similarly, IL-21 was able to inhibit tumour-mediated FOXP3 induction in naïve CD4 T cells and restore their proliferative capacity." (PMID 28239749, 2017). "85% of mice in the 16-21/7 group stayed tumor-free, while only 40% and 20% of mice in the 16–21 group and the 16-7 group were immune to lethal tumor challenge, which suggested a synergy between IL-21 and IL-7 when co-expressed in whole-cell vaccines." (PMID 27571893, 2016). "Thus, enhanced infiltration of CD8+ and CD4+ effector T cells in tumors and altered balance between effector T cells and regulatory T cells in favor of immunity contributed to the augmented efficacy of IL-21 and IL-7 co-expressing tumor cell vaccine." (PMID 27571893, 2016). "Additionally, it has been shown that IL-21 is able to potentiate tumor-specific antibody responses, which resulted in complement-mediated tumor cell lysis." (PMID 27656185, 2016). "We here also show that CD3+CD8− cells infiltrating the tumor tissue are the major source of IL-21." (PMID 25839161, 2015). "Taken together, these results suggest that elevated levels of IL-21 in the tumors of Apcmin/+ mice support a tumor-promoting inflammatory microenvironment characterized by enhanced production of IL-17A, IL-22, TNF-α and IL-6 and hyper-activation of STAT3/NF-kB." (PMID 25839161, 2015). "Taken together, in addition to the negative impact on Th1 differentiation, this cytokine circuit could be another mechanistic feature of IL-6 in converting the function of IL-21 from immunostimulatory to tolerogenic for tumour outgrowth in aged animals." (PMID 25850032, 2015). "IL-21 was significantly increased in CRC samples as compared to non-tumor mucosa." (PMID 25839161, 2015). "These cells are the primary source of IL-21 secretion and antibody production, which might benefit tumor cell elimination." (PMID 26517519, 2015). "Importantly, when Th1 differentiation was restored by the blockade of IL-6 or subsequent IL-4/IL-21 activities, induction of tumour-specific aged CD8+ T cells was enhanced as well, implying minimum intrinsic functional defects in aged CD8+ T cells." (PMID 25850032, 2015). "For example, IL-21 gene transfer promoted the production of tumor-specific IgG, which may contribute to the therapeutic effect in a syngeneic head and neck squamous carcinoma model." (PMID 25961061, 2015). "In addition, IL-21 amplified the effects of an anti-HER2/neu mAb against a Her-2-expressing murine tumor in vivo, through an IFN-γ-dependent effect." (PMID 25961061, 2015).
tumor (continued). "Similar findings were seen when STAT3 and NF-kB activation was assessed by immunohistochemistry, which also revealed a reduction of cells positive for p-STAT3 Y705 and p-NF-kB/p65 Ser536 in both transformed epithelial cells and tumor infiltrating cells in the lesions of IL-21 KO-Apcmin/+ mice." (PMID 25839161, 2015). "An IL-17E enhanced cytotoxicity of TIL-B cells could be discussed as well as it was already demonstrated that B cells stimulated with IL-21 can secrete granzyme B and could have a direct cytotoxicity against tumor cells." (PMID 26154409, 2015). "In addition, interferon- (IFN-) γ and third-order CXCL-9, -10, and -11 antiangiogenic chemokines were soluble mediators of the IL-21-driven tumor rejection and mediated antiangiogenic effects." (PMID 25961061, 2015). "Since our studies have also shown high IL-21 production in the tumor areas of patients with sporadic CRC, we hypothesized that this cytokine can sustain the growth of sporadic CRC." (PMID 25839161, 2015). "In an in vitro study, IL-21, in the presence of IL-2, enhanced the expansion of phosphoantigen-activated human Vγ9Vδ2 T cells and boosted their Th1-like program and cytotoxic activity against tumor cells." (PMID 25961061, 2015). "Besides tumor cells, also other cell types transduced with IL-21 gene proved to be effective at inducing antitumor responses." (PMID 25961061, 2015). "IL-21 was upregulated in the neoplastic areas, as compared with non-tumor mucosa, of Apcmin/+ mice, and genetic ablation of IL-21 in such mice resulted in a marked decrease of both tumor incidence and size." (PMID 25839161, 2015). "Moreover, IL-21's antitumor activity can be potentiated by its combination with other immune-enhancing molecules, monoclonal antibodies recognizing tumor antigens, chemotherapy, or molecular targeted agents." (PMID 25961061, 2015). "Additionally, IL-21 is able to induce tumor regression and increase the survival of mice with xenograft DLBCL tumors." (PMID 24959288, 2014). "Interestingly, the IL-21 aAPC expanded CD8+ T cells demonstrated superior functional tumor recognition, with significantly higher IFNγ release levels than the CD8+ T cells expanded by IL-2 and IL-15 aAPC." (PMID 23402380, 2013). "IL-21 has both immunosuppressive and immunostimulatory effects on anti-tumor immunity." (PMID 22279576, 2012). "IL-21 might be captured by cells that express IL-21R — either tumor cells, as we demonstrated in this study, or Th17 cells themselves." (PMID 21949734, 2011). "The robust GM-CSF and IFN-γ release induced by IL-15 and IL-21 in combination suggests that cytokine-differentiated NK cells may retain the ability to mount effective anti-viral and anti-tumour responses." (PMID 19712464, 2009). "In addition, the ability of IL-21 to promote long-lasting CD8+ T-cell-dependent tumour responses has been shown in athymic mice with intraperitoneal or subcutaneous tumours." (PMID 19712464, 2009). "Mice treated with both IL-21 and IL-2 exhibited the best anti-tumor response." (PMID 16772043, 2006). "Similarly, unvaccinated tumor-bearing control mice which were irradiated and treated with IL-21 or IL-21 + IL-2 only had comparable rapid tumor growth (data not shown)." (PMID 16772043, 2006). "In vivo studies have recently demonstrated that interleukin 21 (IL-21) enhances the anti-tumor function of T-cells and NK cells in murine tumor models, and the combined use of IL-21 and IL-15 has resulted in prolonged tumor regression and survival in mice with previously established tumors." (PMID 16772043, 2006). "In vivo data demonstrate that IL-21 enhances the anti-tumor function of T-cells and NK cells." (PMID 16772043, 2006). "However, combination therapy with IL-21 and IL-2 resulted in the highest long-term (>150 days) tumor-free survival frequency of 46%." (PMID 16772043, 2006).
tumor (continued). "Antitumor effects have been demonstrated for fusion proteins composed of antibodies targeting different tumor-associated antigens (e.g., CEA, EDB, EDA, GD2, EGFR, FAP) and many cytokines of the common gamma chain receptor family (e.g., IL-2, IL-15, IL-15/IL15Rα, IL-21, IL-7)." (PMID 40370435, 2025). "Similarly, in tumor models, tumor‐associated neutrophils upregulate GZB when stimulated with a cytokine mix (IL‐2, IL‐12, IL‐21) alone or combined with a TLR4 agonist, demonstrating that innate (TLR) and adaptive (cytokine) signals converge to trigger neutrophil GZB production." (PMID 41244336, 2025). "Thus, there is a need to consider how NK cells respond to IL-15 and how tumor-localized production of IL-15 (or IL-2, IL-21, or IL-10) is affected by therapeutics and how this therapy can be customized to address the likely insufficient cytokine receptor agonism within the TME." (PMID 40410571, 2025). "Therefore, the presence of IL-21 and IL-22 proteins in serum may reflect changes in the tumour microenvironment." (PMID 40729006, 2025). "Also for CAR-NK cells, it could be demonstrated that the co-expression of IL-21 enhanced anti-tumour activity." (PMID 40650066, 2025). "Notably, cytokine-expressing NK cells, including CD19IL15 CAR-NKs, IL-15 NKs, and IL-21 NKs exhibited a small peak in cytotoxic NK cell ratios, corresponding to the transition of a subset of cytotoxic NK cells into the vigilant phenotype upon tumor clearance." (PMID 40027823, 2025). "Furthermore, IL-15/IL-21 demonstrated an increased capacity to enhance CAR-T tumor killing." (PMID 40291594, 2025). "Therefore, supplementing the IL-21 signal to AFP-TCR-T may support its antitumor function within the HCC tumor microenvironment, which is deprived of the IL-21 signal." (PMID 38643203, 2024). "The aAPC platform was used to rapidly amplify tumour-infiltrating lymphocytes from primary tumour specimens, based on the Carl H June designed aAPC-K32, and further co-transfection with co-stimulatory molecule 4-1BBL and allowing it to secrete IL-2, IL-15, or IL-21 cytokines." (PMID 39215816, 2024). "Numerous immune system lymphoid and myeloid cells are impacted by IL-21 since this cytokine possesses immunomodulatory capabilities that link most of the immune system components, influencing the development, differentiation, and survival of lymphocytes possessing anti-tumor activity." (PMID 37759505, 2023). "The researchers linked IL‐15 and IL‐21 to the anti‐GD2 antibody hu14.18 and found that the two‐novel antibody–cytokine conjugates, hu14.18‐IL15 and ‐IL21, were able to induce complete regression and prolong survival in NB tumor models, which had a stronger ADCC effect than hu14.18‐IL2." (PMID 38090056, 2023). "Hence, it is obvious that IL-21 affects the oncogenic course by managing and redefining the tumor microenvironment through the manipulation of immune-inflammatory pathways given its capacity to affect cell proliferation, immunity, and other crucial biological processes." (PMID 37759505, 2023). "However, it has been also proven that IL-21 not only promotes carcinogenesis and tumour growth, but also, under certain conditions, may have anti-cancer effects and inhibit the angiogenesis process." (PMID 36980527, 2023). "In addition, we investigated whether the antitumor function of IL21 and PD-1 blockade depends primarily on immune responses in the tumor or peripheral lymphoid organs." (PMID 37546701, 2023). "However, Th9 cells produce IL-21 in addition to IL-9, a cytokine with anti-tumor function." (PMID 35514957, 2022). "Importantly, an anti-PD-1 antibody could inhibit only Treg expansion induced by clinical tumor explants with high expression of IL-21/PD-L1." (PMID 34026621, 2021). "Interestingly, other studies have found that IL-21 may be responsible, in part, for the anti-tumor functions of helper CD4+ T cells." (PMID 33809259, 2021).
tumor (continued). "After observing the critical role of BATF downstream of IL-21 signaling in tumor-infiltrating effector CD8+ T cell differentiation, infiltration, and function, we wanted to explore whether BATF overexpression in tumor-specific CD8+ T cells could bypass their need for CD4+ T cell help." (PMID 33809259, 2021). "We believe that this inconsistency may be attributed to that study ignoring the involvement of the tumor microenvironment, and IL-21 may exert double sword effects on Tregs at the context of other immunosuppressive component derived from tumor microenvironment such as PD-L1." (PMID 34026621, 2021). "In the present study, HNSCC tumor-infiltrating lymphocytes (TILs), which secrete typical cytokines associated with Th1-, Th2-, Th9-, Th17-, and Th21-polarized inflammation (including IFN-γ, IL-4, IL-9, IL-17, and IL-21), were identified using flow cytometric analysis." (PMID 34026621, 2021). "Therefore, it likely depends on the status and type of immune infiltrates and the presence of environmental cofactors such as PD-L1 whether anti-tumor immune response is suppressed or supported by IL-21 in tumor microenvironment." (PMID 34026621, 2021). "Indeed, CAR T cells, producing IL-21, have shown increased efficacy against tumor cells in vivo." (PMID 34572932, 2021). "Our results showed that enriched IL-21+ cells and PD-L1 expression were positively associated with FOXP3+ cell infiltration and that high expression of IL-21 and PD-L1 correlated with advanced tumor stage and poor overall and disease-free survival in patients with HNSCC." (PMID 34026621, 2021). "In addition, this work suggests that IL-21, as a component of the tumour microenvironment, may also contribute to the proliferation of EBV-positive DLBCL cells." (PMID 32704112, 2020). "Accordingly, IL-21′s activities may serve to either promote or inhibit tumor progression." (PMID 32069813, 2020). "To verify whether IL-21 accelerates EBV-positive DLBCL cell proliferation in vivo, we established a NOD/SCID mouse xenograft model of EBV-positive DLBCL by subcutaneous inoculation of Farage cells and measured tumour growth after IL-21 (10 μg) treatment once daily for 7 consecutive days." (PMID 32704112, 2020). "In addition, the activation of IL-21 by ruxolitinib is known to act as a costimulatory signal that enhances the effector function of immune cells and activation of T cells, thereby suppressing tumor growth." (PMID 30987642, 2019). "In addition to IL-7, IL-21 has also been reported to promote T cell-mediated tumor rejection." (PMID 31379876, 2019). "Moreover, IL-21 increased invasion of tumor cell lines in a Blimp-1-dependent manner." (PMID 31540511, 2019). "Increases in PD-L1 expression can occur on SCC cells as a result of mutations in tumor cell signaling pathways or exposure of tumor cells to inflammatory cytokines IL-1, IL-6, GM-CSF, IFNγ, TNFα, and VEGF and the gamma-chain cytokines IL-2, IL-7, IL-10, IL-15, and IL-21." (PMID 31554151, 2019). "Furthermore, an IL-21-mediated promotion of tumor cell invasion could be shown in vitro, supporting the notion of the tumor-promoting abilities of cytokines, released by inflammatory cells of the tumor microenvironment." (PMID 31540511, 2019). "However, IL-21 expression was gradually decreased in the mouse tumour sites." (PMID 29966369, 2018). "However, the effects of IL21 on angiogenesis are complicated: in a tumor environment with abundant growth IL-21R activation was shown to be angiostatic, and IL-21 administration decreased tumor vascular density and tumor size in mice bearing EG7 tumor cells via STAT1 activation." (PMID 29358309, 2018). "Furthermore, deletion of IL-21 could further reduce tumor numbers and tumor size in AOM/DSS-treated mice." (PMID 28852270, 2017). "Interestingly, absence of IL-21 caused progressive tumour growth in Grail−/− mice comparable to WT mice." (PMID 28798332, 2017).
tumor (continued). "Thus, expanding Vγ2Vδ2 T cells with pulse zoledronate stimulation and either IL-18/IL-2, IL-21/IL-15, or IL-21/IL-2 could increase their anti-tumor immunity." (PMID 28239463, 2017). "Additionally, IL-21, also produced by Th17 cells, might promote the proliferation of tumor Ag-specific CTLs." (PMID 29163524, 2017). "It remains to be determined whether this effect is relevantin vivo, but in this regard, IL-1β could induce the production of high levels of IL-21 by Th9 cells, but these cells nevertheless continued to produce IL-9 and acquired potent IL-21-mediated anti-tumor activity." (PMID 29123649, 2017). "Next to IL-2, other γc-cytokines, such as IL-7, IL-15, and IL-21, have been described to play a role in memory T cell formation, proliferation, and survival, yet result in a lower degree of T cell differentiation but are still able to enhance anti-tumor responses." (PMID 27656185, 2016). "In addition to IL-9, IL-21 secreted by TH9 cells also exerts critical anti-tumor effects." (PMID 27589682, 2016). "Early studies showed that IL-21 costimulates the proliferation of B, T, and NK cells and mediates the differentiation of activated NK cells into more potent effector cells, suggesting that IL-21 may represent a potentially useful agent for the development of tumor immunotherapies." (PMID 25961061, 2015). "In multiple papers, it has been suggested that exposure to IL-21 alone causes lymphocytes to remain in or differentiate into a minimally differentiated phenotype (CD62L+CD44−), and that these lymphocytes have greater anti-tumor capacity relative to cells expanded in other gamma chain cytokines." (PMID 25903148, 2015). "Although IL-21R−/− mice have normal NK cell numbers, treatment of murine NK cells in vitro with IL-21 reduces NK cell proliferation and survival in the presence of IL-2 or IL-15 but induces terminal differentiation and enhances NK cell cytotoxicity against tumor lines." (PMID 25054077, 2014). "IL-21 has demonstrated substantial antitumor responses in several independent preclinical studies, in which mice inoculated with diverse transplantable syngeneic tumor lines were treated with the drug via cytokine-gene transfection, plasmid delivery, or injection of the recombinant protein." (PMID 22022259, 2011). "Conversely, NKG2D expression levels significantly increased as a result of combined treatment with IL-15 and IL-21, suggesting that the NK cell populations obtained under these culture conditions may represent suitable effectors for cell-based anti-tumour therapeutic approaches." (PMID 19712464, 2009). "Interestingly, IL-21 selectively enhances the effector functions of IL-15-activated murine NK cells, further underpinning the importance of functional interactions between the two cytokines, and mediates potent in vivo anti-tumour responses." (PMID 19712464, 2009). "GPC3-targeting CAR-T cells with dual cytokine expression of IL-15 and IL-21 exhibited enhanced antitumour activity against HCC, demonstrating superior proliferation, persistence, and tumour regression in GPC3-positive xenograft models." (PMID 40624498, 2025). "Furthermore, the presence of tumour cells and the associated inflammation may lead to atypical cytokine secretion patterns, which may explain the lack of correlation between IL-21 and IL-22 in this group, but further detailed studies are needed." (PMID 40729006, 2025). "IL-21 arming augmented the function of CD4+ and CD8+ T cells, potentiated the anti-tumor activity of OVV, and reshaped the tumor immune microenvironment in mouse models of glioblastoma multiforme." (PMID 40821119, 2025). "IL‐21 and IL‐21R expression are decreased in NSCLC patients, and IL‐21 treatment regresses tumor growth and invasion in these patients." (PMID 39083441, 2025).